SOAT1 (sterol O-acyltransferase 1)
Description:
Catalyzes the formation of fatty acid-cholesterol esters, which are less soluble in membranes than cholesterol. Plays a role in lipoprotein assembly and dietary cholesterol absorption. Preferentially utilizes oleoyl-CoA ((9Z)-octadecenoyl-CoA) as a substrate: shows a higher activity towards an acyl-CoA substrate with a double bond at the delta-9 position (9Z) than towards saturated acyl-CoA or an unsaturated acyl-CoA with a double bond at the delta-7 (7Z) or delta-11 (11Z) positions.
Synonyms: ACAT-1; ACACT; ACAT; ACAT1; SOAT; STAT
Tractability: Small molecule: an approved drug acts on it; a structure with a bound ligand is known; a high-quality ligand is known; it belongs to a druggable protein family. Antibody: UniProt predicts a signal peptide or a membrane-spanning region. PROTAC: ubiquitination databases record sites on it; its protein half-life has been measured; a small molecule that binds it is known.
Target class: Enzyme; Transferase
Gene: Protein-coding gene on chromosome 1 (179,293,440 to 179,358,680, forward strand). Ensembl gene ENSG00000057252.
Subcellular location: Endoplasmic reticulum membrane
Subcellular location (Human Protein Atlas): Endoplasmic reticulum
Pathways (Reactome):
Transport of small molecules: LDL clearance
Gene Ontology:
Molecular function: cholesterol binding; cholesterol O-acyltransferase activity; fatty-acyl-CoA binding; protein binding; sterol O-acyltransferase activity
Biological process: cholesterol efflux; cholesterol homeostasis; cholesterol metabolic process; cholesterol storage; macrophage derived foam cell differentiation; positive regulation of amyloid precursor protein biosynthetic process; very-low-density lipoprotein particle assembly; low-density lipoprotein particle clearance
Cellular component: endoplasmic reticulum; endoplasmic reticulum membrane; membrane
Genetic constraint (gnomAD): Loss-of-function variants: 29 observed, 40.03 expected, observed/expected ratio (o/e) 0.72, 90% interval 0.54 to 0.99. The upper end of that interval is the gene's LOEUF score, 0.99, which puts it in group 4 of 6, group 1 being the genes least tolerant of losing a copy. Missense variants: 398 observed, 473.49 expected, observed/expected ratio (o/e) 0.84, 90% interval 0.77 to 0.91. Synonymous variants: 163 observed, 166.67 expected, observed/expected ratio (o/e) 0.98, 90% interval 0.86 to 1.11.
Homologues: Orthologues: chimpanzee SOAT1 (100% identical), macaque SOAT1 (98% identical), rabbit SOAT1 (91% identical), dog SOAT1 (90% identical), rat Soat1 (86% identical), mouse Soat1 (85% identical), pig SOAT1 (85% identical), guinea pig SOAT1 (83% identical), tropical clawed frog soat1 (68% identical), zebrafish soat1 (59% identical), Drosophila melanogaster CG8112 (33% identical), Caenorhabditis elegans mboa-1 (29% identical). Paralogues in human: SOAT2 (45% identical), DGAT1 (22% identical).
Diseases named in the same sentence as SOAT1 in open-access papers:
SOAT1 is named in the same sentence as 726 diseases in open-access papers, as found by Europe PMC text mining. Sharing a sentence is not in itself a finding about the gene and the disease. The quoted sentences say what the papers report.
breast carcinoma (261 papers, 2010 to 2026). "According to Huang’s pan-cancer analysis, the SOAT1 gene exhibits increased expression in various cancers, such as lung adenocarcinoma, lung squamous cell carcinoma, breast cancer, hepatocellular carcinoma, and gastric cancer." (PMID 40223054, 2025). "SOAT1 was identified as an over-expressed gene in the claudin-low intrinsic subtype of breast cancer." (PMID 34201030, 2021). "The SOAT1 inhibitor CP-113818 reduced proliferation of breast cancer cells and specifically inhibited LDL-induced proliferation of ERα- cells." (PMID 32194787, 2020). "Another study showed that breast cancer cell lines treated with auraptene, a naturally occurring SOAT1 inhibitor, also had decreased cellular proliferation, invasion, and colony formation." (PMID 32194787, 2020). "Accordingly, a down-regulation of SOAT1 expression after n-3 PUFA treatment has been observed in human breast cancer cells." (PMID 23241455, 2012). "The potential role of CE or SOAT1 in breast cancer remains poorly understood." (PMID 34201030, 2021). "Exogenous and endogenous CE can increase mammary tumor growth and sterol acyltransferase SOAT1 may be a potential target for the treatment of breast cancer." (PMID 34201030, 2021). "Our data suggest that SOAT1, a sterol O-acyltransferase, may be a potential target for the treatment of breast cancer." (PMID 34201030, 2021). "Therefore, we investigated the effect of exogenous and endogenous CE, using diet and SOAT1 inhibitor avasimibe, on tumor growth in a mouse mammary tumor model." (PMID 34201030, 2021). "In breast cancer, the top-ranked gene was ACAT1 (Acetyl-CoA acetyltransferase, not be confused with the enzyme acyl-Coenzyme A: cholesterol acyltransferase 1, which is encoded by the gene SOAT1)." (PMID 25961905, 2015).
melanoma (135 papers, 2007 to 2026). A malignant, usually aggressive tumor composed of atypical, neoplastic melanocytes. "Inhibition of SOAT1 leads to recovered function and enhanced T cell proliferation in melanoma model mice." (PMID 37304239, 2023). "Also, targeting SOAT1 via avasimibe could enhance the killing effect of CD8 + T cells on melanoma by elevating membrane cholesterol content; thus, promoting T-cell receptor (TCR) aggregation and immune synapse formation." (PMID 33637695, 2021).
glioma (131 papers, 2010 to 2025). A benign or malignant brain and spinal cord tumor that arises from glial cells (astrocytes, oligodendrocytes, ependymal cells). "Research reports that SOAT1 is upregulated in glioma tissues compared to normal brains, and high SOAT1 expression is associated with poor prognosis." (PMID 40097417, 2025). "First, the glioma cell lines were transfected with specific siRNA to knock down the mRNA expression of SOAT1, which was the main contributor of the risk signature." (PMID 37488496, 2023). "This study investigates the role of SOAT1, a key gene involved in cholesterol esterification, in glioma prognosis and its association with ferroptosis." (PMID 37980334, 2023). "In the present study, the prognostic value of SOAT1 in glioma and its association with immune cell infiltration was elucidated." (PMID 35646697, 2022). "Metabolic reprogramming is a hallmark of glioma, and sterol O-acyltransferase 1 (SOAT1) is an essential target for metabolic therapy." (PMID 35646697, 2022). "SOAT1 is mostly expressed in glioma-associated macrophages but less in glioblastoma cells." (PMID 40097417, 2025). "Similarly, SOAT1, overexpressed in glioma tissues, is implicated in inhibiting ferroptosis and promoting radioresistance through the PI3K-AKT-mTOR signaling pathway." (PMID 38562143, 2024). "Recently, high expression of SOAT1 was also found in glioma-associated macrophages, suggesting that inhibition of SOAT1 might also trigger an immune response to GBM cells." (PMID 36009491, 2022). "Since FoxP3+ Tregs play a crucial role in glioma-mediated immunosuppression, we wonder whether the SOAT1 expression was associated with immunosuppression in glioma." (PMID 35646697, 2022). "In addition, it was found that the high SOAT1 expression was associated with malignant pathological characteristics in glioma, indicating that lipid metabolism was linked to glioma heterogeneity and excessive lipid metabolism indicated a malignant subtype." (PMID 35646697, 2022). "Our evidence showed the SOAT1 higher expression in higher grade and astrocytoma phenotype may explain the association of SOAT1 with poor prognosis in glioma." (PMID 35646697, 2022). "In the present study, as the most important contributor of the risk signature (Regression coefficients = 0.2773), the biological function of SOAT1 were also investigated in glioma cell lines." (PMID 37488496, 2023). "Recent studies have identified elevated expression of SOAT1 and increased cholesteryl ester content in various cancer types, including glioma, pancreatic cancer, prostate cancer, lung cancer, and adrenocortical carcinoma." (PMID 37980334, 2023). "In summary, this study uncovers the pivotal role of SOAT1 as a link between cholesterol esterification and ferroptosis in glioma." (PMID 37980334, 2023). "In our study, we investigated the impact of SOAT1 on the sensitivity of glioma cells to ferroptosis both in vivo and in vitro." (PMID 37980334, 2023). "We show that inhibiting SOAT1 enhances the efficacy of radiotherapy in gliomas, both in vitro and in vivo, by promoting sensitivity to ferroptosis." (PMID 37980334, 2023). "SOAT1 esterifies cholesterol into a cholesteryl ester and promotes the formation of lipid droplets; therefore, we studied the expression of SOAT1 in normal brain and glioma specimens." (PMID 37980334, 2023). "In glioma, SOAT1 has been found to correlate with poor prognosis, advanced malignancy, and specific clinicopathological characteristics." (PMID 37980334, 2023). "Our findings underscore the potential of SOAT1 as a promising clinical therapeutic target, providing new avenues for the development of effective treatments for glioma." (PMID 37980334, 2023). "We found that the key enzyme in cholesterol esterification, SOAT1, affected the sensitivity of glioma cells to ferroptosis and RT in vivo and in vitro." (PMID 37980334, 2023).
glioma (continued). "In conclusion, our findings demonstrate that SOAT1 influences the sensitivity of glioma cells to ferroptosis by modulating SLC40A1." (PMID 37980334, 2023). "In this study, we demonstrate that inhibiting SOAT1 increases the sensitivity of glioma cells to ferroptosis, both in vitro and in vivo." (PMID 37980334, 2023). "Then, we performed CCK-8 and transwell migration assays to further evaluate the function of SOAT1 in glioma cell lines." (PMID 37488496, 2023). "A protein-protein interaction network was established, and co-expression analysis was conducted to investigate the regulatory mechanism of SOAT1 in glioma." (PMID 35646697, 2022). "Consistently, our analysis showed that CMTM6 expression was strongly correlated with SOAT1 expression in glioma, further evidence revealing the connection between metabolic remodeling and tumor immune escape." (PMID 35646697, 2022). "In combination, SOAT1 was widely overexpressed in a variety of tumors, and the high SOAT1 expression was found to be correlated with malignant clinicopathological characteristics in glioma." (PMID 35646697, 2022). "We divided patients into high/low groups by the median value of SOAT1 expression and performed the survival analysis in each type of glioma." (PMID 35646697, 2022). "It was found that SOAT1 had a marked predictive ability for the 1-, 3-, and 5-year OS of overall and grade 3 gliomas." (PMID 35646697, 2022). "Unfortunately, no statistical significance of survival analysis was identified between SOAT1 -high and -low groups in all types of gliomas." (PMID 35646697, 2022). "Using RNA-seq and clinical data of glioma patients from The Cancer Genome Atlas (TCGA), SOAT1 was found to be correlated with poor prognosis in glioma and the advanced malignancy of clinicopathological characteristics." (PMID 35646697, 2022). "The survival area under the curve (AUC) of SOAT1 expression was 0.766, 0.744, and 0.708 for the 1-, 3-, and 5-year OS, respectively, in overall glioma." (PMID 35646697, 2022). "To investigate the relationship between SOAT1 and ferroptosis in gliomas, we constructed a lentivirus-mediated RNAi targeting SOAT1 (shSOAT1, #1: 5’-TTGAACTCAAGTACCAGCCTTC-3’; #2: 5′-TAATGGTCGAATTGACATAA-3′) in glioblastoma U-87MG cells and astrocytoma U-251 cells." (PMID 37980334, 2023). "We found that knockdown of SOAT1 could significantly suppressed the proliferation and migration capability of glioma cells." (PMID 37488496, 2023). "Immunofluorescence staining was used to observe the expression changes and localization of SOAT1 in normal tissues and glioma tissues, and further western blot experiments showed that the expression of SOAT1 in glioma tissue cells was significantly increased compared with paired normal tissues." (PMID 37980334, 2023). "In glioma, increased SOAT1 expression correlated with multiple infiltrating immune cells." (PMID 37304239, 2023). "The results showed that silencing SOAT1 expression suppressed the proliferation and migration capacity of glioma cells, which may provide novel target for the treatment of gliomas." (PMID 37488496, 2023). "Lipid droplets were previously thought to be inert organelles, however glioblastoma has demonstrated higher SOAT1 expression compared to less malignant astrocytomas, and an inverse correlation has been observed between the number of cytoplasmic lipid droplets in gliomas and prognosis." (PMID 37980334, 2023). "Although the impact of SOAT1 on glioma prognosis has been recognized, its precise mechanism remains unclear." (PMID 37980334, 2023). "This suggests that targeting SOAT1 could potentially improve therapeutic outcomes for glioma patients." (PMID 37980334, 2023). "Using K-M curves and log-rank tests, the high SOAT1 expression was found to be associated with poor prognosis in overall and grade 3 gliomas, but not in grade 2 gliomas and GBM." (PMID 35646697, 2022).
glioma (continued). "LD accumulation and increased SOAT1 expression have been discovered in glioma, whereas the relationship between SOAT1 expression and immune infiltration in glioma remains unclear." (PMID 35646697, 2022). "In addition, univariate Cox regression analysis indicated that SOAT1 was a poor prognostic factor for glioma patients; the HR (95% CI) was 2.863 (2.358-3.477)." (PMID 35646697, 2022). "In addition, the correlation between SOAT1 expression and the clinicopathological characteristics of gliomas was investigated using clinical and transcriptome (RNA-seq) data from TCGA." (PMID 35646697, 2022). "Since IDH wild type and 1p19q non-co-deletion are malignant biomarkers of glioma, the high SOAT1 expression may predict the advanced malignancy of glioma." (PMID 35646697, 2022). "Previously, the SOAT1 inhibitor avasimibe was reported to have reliable therapeutic effect through reducing the incidence of cancers, including liver cancer, pancreatic cancer, glioma, ovarian cancer, and lung carcinoma." (PMID 34914638, 2022). "Since LD is formed by the aggregation of CEs, it is not surprising that the expression of SOAT1 is associated with M2 macrophage infiltration in glioma." (PMID 35646697, 2022). "Not surprisingly, SOAT1 expression was associated with poor prognosis in all gliomas taken together but it has no prognostic significance in individual glioma type and grade." (PMID 35646697, 2022). "In combination, these genes may play a significant role in the regulatory mechanism of SOAT1 in gliomas." (PMID 35646697, 2022). "Furthermore, by comparing the mRNA levels of SOAT1 in glioma tissues and corresponding normal tissues in a comprehensive dataset (TCGA-GBM plus TCGA-LGG), the mRNA level of SOAT1 in glioma was significantly upregulated, and the expression of SOAT1 increased with an increase in tumor grade." (PMID 37980334, 2023). "In addition, various BPs and signaling pathways that SOAT1 may be involved in during glioma pathogenesis were explored." (PMID 35646697, 2022). "Therefore, the prognostic value of SOAT1 in glioma was comprehensively explored." (PMID 35646697, 2022). "Finally, differentially expressed gene analysis, and Gene Ontology and Kyoto Encyclopedia of Genes and Genomes analyses were performed to explore the biological processes and signaling pathways that SOAT1 may be involved in during glioma pathogenesis." (PMID 35646697, 2022). "Finally, multiple genes that may interact with SOAT1 in gliomas were identified via PPI network and co-expression analyses." (PMID 35646697, 2022). "Inhibition of SOAT1 regulates SLC40A1 through the PI3K/AKT/mTOR pathway, elevating the level of lipid peroxidation in glioma cells and enhancing their sensitivity to ferroptosis inducers and radiotherapy." (PMID 40583858, 2025). "The SOAT1 expression of isocitrate dehydrogenase (IDH) wild type was higher than that of IDH mutant type in WHO grade 3 and overall gliomas." (PMID 35646697, 2022). "Thus far, SOAT1 has exhibited a prognostic value in several types of cancers, and its blockade can inhibit the proliferation of neoplasm cells in various cancer types, including pancreatic cancer, glioma, prostate cancer, lung cancer, and adrenocortical carcinoma." (PMID 35646697, 2022). "The AUC of SOAT1 expression was 0.755, 0.645, and 0.603 for the 1-, 3-, and 5-year OS, respectively, in WHO grade 3 gliomas." (PMID 35646697, 2022). "The mechanism through which SOAT1 influences radioresistance is not explicitly detailed, but the link between SOAT1-mediated ferroptosis modulation and the response of glioma cells to radiotherapy is clearly evident." (PMID 38562143, 2024). "In summary, high expression of SOAT1 and SLC40A1 can reduce the level of lipid peroxidation, thereby reducing the conversion of cholesterol to cholesterol esters and inhibiting ferroptosis in glioma cells." (PMID 37980334, 2023). "The prognostic value of SOAT1 in glioma has not been fully elucidated, so it was explored herein." (PMID 35646697, 2022).
glioma (continued). "SOAT1 expression in 1p19q non-co-deleted gliomas was higher than that of 1p19q-co-deleted gliomas." (PMID 35646697, 2022). "Furthermore, we also found that correlation between SOAT1 expression and Treg infiltration was not strong in glioma." (PMID 35646697, 2022). "Therefore, silencing SOAT1 may significantly reduce the survival rate of glioma cells under RT by increasing the level of lipid peroxidation, whereas SLC40A1 OE and DFO, increases the survival rate of glioma cells by reducing the level of lipid peroxidation." (PMID 37980334, 2023).